CD47 (CD47 molecule)
Diseases named in the same sentence as CD47 in open-access papers (continued):
Sharing a sentence is not in itself a finding about the gene and the disease.
periodontal disease (1 paper, 2024). "To comprehend the mechanisms underlying the inhibitory effect of GV1001 on elevated levels of CD47 in aortic roots in mice with Pg-induced periodontal disease, we conducted in vitro studies using human coronary artery smooth muscle cells (HCASMCs)." (PMID 38892314, 2024). "Pg-induced periodontal disease led to the infiltration of Pg, Pg LPS, and gingipains in the arterial wall, concurrently with the induction of vascular inflammation and an increase in CD47 expression." (PMID 38892314, 2024). "However, the immunofluorescent staining level of CD47 in the aortic roots significantly increased in mice with Pg-induced periodontal disease compared to the controls, and GV1001 administration remarkably inhibited the staining intensity of CD47 in aortic roots." (PMID 38892314, 2024).
prion disease (1 paper, 2017). A transmissible disease that is caused by a protein that is able to induce abnormal folding of normal cellular proteins, leading to characteristic spongiform brain changes, which are associated with neuronal loss without an inflammatory response. "Sirpa and Cd47 mRNA levels showed some fluctuations during the progression of prion diseases, with some degree of variation based on mouse and prion strain combination, and the same occurred also to Mfge8 levels." (PMID 28545141, 2017). "In addition, we analysed Sirpa, Cd47, Aif1, Trem2 and Mfge8 mRNA levels selectively in hippocampus and cerebellum at different time points during the progression of prion disease using RNA sequencing." (PMID 28545141, 2017).
prostate adenocarcinoma (1 paper, 2019). "Analysis of tumor data in TCGA also implicated CD47 regulation of SLFN11 promoter methylation in a subset of cancers that includes prostate adenocarcinoma." (PMID 31632920, 2019).
pulmonary disease (1 paper, 2019). "Therefore, targeting CD47 could be considered as a potential intervention to limit sequelae due to radiation-lung disease." (PMID 31597291, 2019).
retinal degeneration (1 paper, 2021). Degeneration of the retina. "Where does CD47 fit in the landscape of emerging treatments for retinal degeneration?" (PMID 34197341, 2021).
retinoblastoma (1 paper, 2019). A malignant tumor that originates in the nuclear layer of the retina. "While CD47 has not been directly linked to DNA repair pathways, its ligand TSP1 is reported to induce γ-H2AX in retinoblastoma." (PMID 31597291, 2019).
rheumatic carditis (1 paper, 2025). "Additionally, in inflammatory valvular diseases resembling rheumatic carditis, CD47 is upregulated on apoptotic cells, and blocking CD47 improves macrophage-mediated clearance, reduces pro-inflammatory cytokine production (e.g., IL-6, TNF-α), and limits fibrosis." (PMID 41303525, 2025).
sarcoidosis (1 paper, 2016). Sarcoidosis is a multisystemic disorder of unknown cause characterized by the formation of immune granulomas in involved organs. "In the whole blood assay used in the present study, we did not demonstrate that the IL-10 regulatory axis was dysfunctional in sarcoidosis, and the expression profiles of regulatory SIRP-α/CD47 were also similar between sarcoidosis and healthy subjects." (PMID 27929051, 2016). "Similarly, expression of CD47, the ligand for SIRP-α/β, was the same in sarcoidosis and controls (data not shown)." (PMID 27929051, 2016).
schizophrenia (1 paper, 2014). A major psychotic disorder characterized by abnormalities in the perception or expression of reality. "In particular, the expression of CD47 is down-regulated in Brodmann area 46 in the prefrontal cortex, and up-regulated in whole blood of patients with schizophrenia." (PMID 24586890, 2014). "It is notable that a few studies reported that expression of CD47 is dysregulated in patients with psychiatric disorders including schizophrenia and attention deficit hyperactivity disorder (ADHD)." (PMID 24586890, 2014). "The present study suggests that CD47 deficiency in mice leads to decreased PPI, and, potentially, abnormal social behavior, both of which are considered to be behavioral abnormalities relevant to schizophrenia." (PMID 24586890, 2014). "CD47 KO mice may thus recapitulate selected aspects of schizophrenia and ADHD, suggesting that CD47 may represent a new therapeutic target for these conditions." (PMID 24586890, 2014).
steatosis (1 paper, 2025). Increased lipid within the cytoplasm of cells. "CD47 deficiency enhances NF-κB activation, elevates IL-1β, TNFα, IL-6, reduces IL-10, increases CCL2 and macrophage infiltration, leading to exacerbated steatosis, inflammation, and fibrosis." (PMID 40630093, 2025). "Global and sustained CD47 deficiency resulting from genetic knockout may elicit compensatory responses that disrupt lipid metabolic homeostasis, potentially impairing lipid export via downregulation of apolipoproteins or undermining innate hepatic defense mechanisms against steatosis." (PMID 40630093, 2025).
T-cell deficiency (1 paper, 2022). "In preclinical studies, the anti-tumor effects of CD47-blockade were abrogated by T-cell deficiency, with substantial improvement in responses seen with the combined use of PD-L1 and CD47 antibodies." (PMID 35883692, 2022).
T-cell leukemia (1 paper, 2022). A malignant disease of the T-lymphocytes in the bone marrow, thymus, and/or blood. "Flow cytometry analysis showed that CD47 cross-dressing occurred in both CD47KO human T-cell leukemia Jurkat cells and pig B-lymphoma LCL cells after incubation for 2 or 6 hr with PAOC47h2 cell-derived EVs." (PMID 36454036, 2022). "In the present study, CD47 cross-dressing was found in human T-cell leukemia Jurkat and pig B-lymphoma LCL cells, suggesting a possible involvement of CD47 cross-dressing in the formation of a tumor immunosuppressive microenvironment." (PMID 36454036, 2022). "CD47 expression and CD47 cross-dressing on human T cell leukemia Jurkat cells." (PMID 36454036, 2022). "We next determined whether cells can be cross-dressed by native CD47 using human T-cell leukemia Jurkat cells that express a higher level of CD47 than normal hematopoietic cells." (PMID 36454036, 2022).
thyroid tumor (1 paper, 2024). A benign or malignant neoplasm affecting the thyroid gland. "Presumably, coexpression of these genes in thyroid tumors is mediated by factors that coordinately induce both CD47 and IFT57 mRNA expression." (PMID 39201643, 2024).
uremia (1 paper, 2026). A clinical syndrome associated with the retention of renal waste products or uremic toxins in the blood. "We then investigated morphological changes in the thoracic aorta to determine the impact of uremia and disrupted CD47 signalling." (PMID 41596404, 2026).
uveitis (1 paper, 2022). An inflammatory process affecting a part of or the entire uvea. "In this study, we demonstrate the contrasting role of TSP-1 in acute vs. chronic models of experimental uveitis and examine the influence of CD47-mediated signaling on leukocyte adhesion in a chronic model of uveitis and its impact on the clinical disease course." (PMID 35628515, 2022).
vector-borne disease (1 paper, 2024). An infectious disease where a pathogen is carried and transmitted by another organism that acts as disease vector. "Understanding how cross-phyla signaling influences host responses suggests new ways to prevent vector-borne diseases and raises the possibility that Nest1 may be useful to treat human illnesses that are amenable to CD47-mediated intervention." (PMID 39121194, 2024).
vesicoureteral reflux (1 paper, 2017). Abnormal flow of urine from the urinary bladder back into the ureters. "For mice that had elevated Cd confined to the urinary tract (i.e. kidney and bladder), we postulate the distribution pattern is related to vesicoureteral reflux of anti-CD47-QD from the bladder into the kidneys." (PMID 28839158, 2017).
vivax malaria (1 paper, 2019). "Expression of CR1, CD55, CD59, and CD47 was also assessed on reticulocytes during falciparum and vivax malaria and healthy controls." (PMID 31533836, 2019).
tumor (1,913 papers, 2007 to 2026). "As expected, CD47-deficient tumor cells were robustly phagocytosed, reflecting the loss of the “don’t eat me” signal." (PMID 41601654, 2026). "In contrast, loss of TRAF2 facilitated CD47 autophagic degradation and inhibited tumor immune escape." (PMID 39665172, 2025). "CD47 is overexpressed in many tumors and is associated with poor overall survival, suggesting that tumor cells have evolved to upregulate the expression of CD47 to escape immune mediated clearance." (PMID 40078999, 2025). "Cd274 (encoding PD-L1), Cd47, and Sirpa, all implicated in tumor immune escape, were also all significantly upregulated." (PMID 41445746, 2025). "Although cancer cell‐derived EVs carry substantial tumor‐associated antigens, the anti‐phagocytic signals present on the surface of cancer cell‐derived EVs, such as CD47, lead to immune evasion of DCs and macrophages." (PMID 40600457, 2025). "One strategy to combine the benefits of a tumor-restricted CD47 blockade with a pro-phagocytic stimulus in a single molecule is to fuse SIRPα with a tumor-associated antigen (TAA)-specific IgG1 antibody." (PMID 40402266, 2025). "By modulating immune checkpoint pathways, such as the CD47-SIRPα axis, PCEs reprogram immunosuppressive tumor-associated macrophages (TAMs) into pro-inflammatory M1 phenotypes, promoting phagocytosis and antigen presentation." (PMID 39982231, 2025). "Overall, the differences between tumor models in their response to NDV and CD47 blockade highlight the importance of identifying tumor characteristics that predict susceptibility to different immunotherapeutic approaches." (PMID 41322194, 2025). "Due to its strong collagen affinity, CBD-SIRPαFc accumulates more rapidly and persists longer at tumor sites, potentially preventing off-target CD47 blockade and its associated adverse reactions." (PMID 40721833, 2025). "Concurrently, Ir1-mediated PDT triggers immunogenic cell death (ICD) via ferroptosis-necroptosis synergy and blocks the CD47-SIRPα immune checkpoint, while promoting M1-polarization of tumor-associated macrophages." (PMID 41298247, 2025). "High infiltration of CD36 + M2 tumour-associated macrophages (TAMs) and elevated CD47 expression in NEPC cells are often associated with poor progression-free survival in cancer patients." (PMID 41163221, 2025). "Delivery methods, including nanoparticles and oncolytic viruses encoding anti-CD47 IgG1 have shown improved tumor specificity and reduced systemic exposure." (PMID 40867316, 2025). "Abundant expression of CD47 is utilized by cancer cells as a mean to escape destruction by tumor-associated macrophages." (PMID 41233805, 2025). "Interactions, such as those mediated by signal regulatory protein alpha chain (SIRPα)- integrin-associated protein (CD47), between macrophages and immunosuppressive T cells influence tumor progression." (PMID 41035074, 2025). "CD47 is a “don’t eat me” signal that is overexpressed in tumors to evade phagocytosis by tumor associated macrophages (TAM)." (PMID 41415295, 2025). "Acting as a dual-targeting bridging protein, OMV-CD47nb simultaneously binds to CD47 on tumor cells and to TLR on tumor-associated macrophages (TAMs)." (PMID 41322140, 2025). "Beyond macrophage fusion, overexpression of CD44 and CD47 in colorectal cancer has been associated with advanced tumour progression, distant metastasis, and a reduced disease-free survival rate." (PMID 39967663, 2025). "Therapeutic efficacy proved dependent on both PEP20-mediated CD47 blockade and ferroptosis induction, as evidenced by diminished tumor control in PEP20-deficient (ix group) and deferoxamine-treated (xi group) cohorts." (PMID 40892295, 2025). "In the GBM microenvironment, this CD47–SIRPα axis promotes immune evasion by supporting the polarisation of tumour‐associated macrophages (TAMs) toward an immunosuppressive M2 phenotype." (PMID 41195773, 2025).
tumor (continued). "Recently, a study focusing on non-Hodgkin’s lymphoma demonstrated that CD47 (a tumor stemness-associated gene) is highly upregulated in the tumor cells of some patients, and is resistant to monoclonal antibody (rituximab) therapy." (PMID 40150683, 2025). "HDACi administration reprogrammed tumor-associated macrophages (TAMs) through dual mechanisms that are dependent on CD47." (PMID 39994810, 2025). "As a small molecule inhibitor, RRx-001 can polarize the low phagocytic M2 phenotype of tumor-associated macrophages to a high phagocytic M1 phenotype, and can decrease the levels of CD47 on cancer cells and SIRPα on macrophages simultaneously." (PMID 40548122, 2025). "In our previous studies, we engineered an oncolytic adenovirus encoding CD47 antibodies (oAd-CD47), designed to enhance macrophage-mediated phagocytosis by blocking CD47 expression on tumor cells." (PMID 40814015, 2025). "We then map the specific treatments of SIRPα-CD47 inhibition for MC38 tumor cells in WT and SIRPα-deficient mice according to their phagocytosis values (φm) as cross-sections through the 3D space." (PMID 41296731, 2025). "In particular, aberrant overexpression of CD47 is a hallmark of immune escape in multiple tumor types, effectively suppressing macrophage‐mediated efferocytosis." (PMID 41403915, 2025). "Our analysis corroborates these findings, revealing that high CD47 expression is significantly linked to advanced clinical stages and poor tumor differentiation, thereby emphasizing its role as a prognostic indicator." (PMID 40765033, 2025). "This combination polarizes tumor-associated macrophages to the M1 phenotype and blocks the “don’t eat me” signal (CD47-SIRPα), enhancing macrophage-mediated phagocytosis." (PMID 40142970, 2025). "Specifically, CD47 expressed on tumor cells interacts with its receptor on M1-like tumor-associated macrophages (TAMs), thereby impairing their phagocytic activity." (PMID 40963868, 2025). "Repolarizing immunosuppressive M2-phenotype tumor-associated macrophages (TAMs) and blocking the CD47/SIRPα axis are promising strategies to enhance cancer immunotherapy." (PMID 42039278, 2025). "In tumours, elevated CD47 expression is commonly associated with impaired immune clearance of cancer cells by macrophages." (PMID 41163221, 2025). "This is particularly notable given emerging evidence that tumor-associated macrophages (TAMs) can directly phagocytose viable cancer cells via modulation of the CD47/CXCR4/CXCL12 axis, a process referred to as “immune surrender”." (PMID 40563669, 2025). "The combination of targeted therapies and CD47 blockade is effective in mouse tumor models bearing driver mutations." (PMID 38483480, 2024). "Specifically, CD47 interacts with SIRPα on tumor‐associated macrophages, inhibiting macrophage‐mediated phagocytosis and promoting immune evasion." (PMID 39297408, 2024). "High CD47 expression was associated with tumor mutation burden and microsatellite instability in certain cancers, which are both associated with response to ICI." (PMID 38493445, 2024). "In thyroid cancer, intervention in a mouse model using anti-CD47 antibody revealed increased tumor-associated macrophage infiltration, enhanced phagocytosis of tumor cells and inhibited tumor growth." (PMID 39652550, 2024). "One highly attractive combination is the inhibition of the ‘don’t-eat-me’-signal CD47, which is known to increase the phagocytic potential of tumor-associated macrophages." (PMID 38357194, 2024). "First, we investigated the association of CD47 expression with tumor grade, metastases, and death occurrence." (PMID 38493445, 2024). "Dual-target bispecific antibodies targeting CD47 and tumor-associated antigens (TAA) or tumor-specific antigens (TSA) have been designed to alleviate hematotoxicity." (PMID 38783333, 2024).
tumor (continued). "One such therapeutic strategy involves increasing the phagocytotic capabilities of tumor-associated macrophages by modulating macrophage–tumor cell surface signaling via the CD47-SIRPα axis." (PMID 38319147, 2024). "have designed a non-pathogenic Escherichia coli strain, which can colonize tumors and locally release an encoded nanobody antagonist of CD47, increasing the activation of tumor-infiltrating T cells, and generating anti-tumor immunity." (PMID 39034996, 2024). "The ECM was found to be involved in CD47-mediated macrophage phagocytosis signaling through the expression of the tumor-associated extracellular matrix protein tenascin C (TNC)." (PMID 39033204, 2024). "CD47 blockade aims to enhance phagocytosis by tumor-associated macrophages (TAMs), which display an M2-like phenotype." (PMID 38414061, 2024). "Given the presence of an immunosuppressive tumor microenvironment in the context of CD47 blockade, it is imperative to elucidate the underlying mechanism and devise a strategy to enhance the efficacy of anti-CD47 therapy." (PMID 38532108, 2024). "Clinical evidence has revealed that CD47-SIRPα interaction in tumor-associated macrophages is a pro-tumorigenic factor and predictor of survival." (PMID 39696410, 2024). "Increasing the phagocytotic capabilities of tumor-associated macrophages by modulating macrophage–tumor cell surface signaling via the CD47-SIRPα axis is a novel strategy." (PMID 38319147, 2024). "Due to its association with tumor immunity evasion, we assessed the associations between CD47 expression levels and the infiltration of MDSCs, CAFs, M2-TAMs, and Treg cells through six algorithms (QUANTISEQ, XCELL, CIBERSORT, CIBERSORT-ABS, TIDE, MCPCOUNTER)." (PMID 38720108, 2024). "Currently, commonly used strategies are preventing these processes, depleting and reprogramming TAMs (tumour-associated macrophages), and blocking “CD47–SIRPα pathways”." (PMID 39408718, 2024). "Main side effects are associated with non-tumor targeted binding to CD47 particularly on blood cells." (PMID 38720892, 2024). "The second is to carry a PD-L1/CD47 nanoantibody that can be delivered to the TME to promote tumour-associated macrophage remodelling to an antitumor state." (PMID 38561367, 2024). "These novel strategies not only aim to mitigate the hematologic toxicity and adverse effects associated with CD47 monoclonal antibodies but also seek to enhance the anti-tumor efficacy of CD47 blockade." (PMID 38720108, 2024). "To date, however, the ubiquitous expression of CD47 on healthy cells causes off-tumor toxicities in most patients." (PMID 39039207, 2024). "We aim to investigate the expression of CD68 and CD47 in patients with different histological variants of CC, tumor characteristics, and burden." (PMID 39201801, 2024). "Functionally, tumor cells with genetic deficiency in oxidative phosphorylation or autophagy are resistant to CD47-SIRPα blockade." (PMID 38982116, 2024). "The immune checkpoint CD47 has recently gained attention as a potential target for intervention as it conveys a “don’t eat me” signal to tumor-associated macrophages (TAMs) via the inhibitory SIRP alpha protein." (PMID 39194679, 2024). "Many studies have reported increased expression of CD47 on neoplastic cells and associations of higher tumor CD47 expression with decreased survival." (PMID 38495618, 2024). "Studies have found that increased CD47 expression is associated with enhanced anti-phagocytic potential of the tumor cells and poor prognosis." (PMID 39795582, 2024). "We envision that our findings on influence of B2m extend beyond the hematopoietic system, impacting tumor-associated macrophages (TAMs) and anti-CD47 treatment efficacy in tumors with high MHC-I." (PMID 39264994, 2024). "The transmembrane inhibitory SIRPα on macrophages interacts with the integrin-associated protein (IAP) CD47, a transmembrane protein with high expression in malignant tumour cells." (PMID 36900335, 2023).